MUC2 (mucin 2, oligomeric mucus/gel-forming)
Diseases named in the same sentence as MUC2 in open-access papers (continued):
Sharing a sentence is not in itself a finding about the gene and the disease.
tumor (continued). "Immunostaining with CK7 and MUC2 was useful for diagnosing collision tumor when the histology was similar to each other." (PMID 36207547, 2022). "MUC2 expression correlated with higher tumor grade (p = 0.0044), a more expansive border (p = 0.044) but with less lymphatic and venous invasion (p = 0.0096, p = 0.0023, respectively)." (PMID 34475526, 2022). "Loss of MUC2, HSPB8, and SCG2 completely disrupted the formation of tumor spheroids in cells expressing ZEB1." (PMID 35440541, 2022). "Risk factors with a p value less than 0.1, i.e., tumour grade, tumour stage, CA19-9 level, adjuvant chemotherapy, adjuvant radiotherapy, MUC1 expression, and MUC2 expression, were integrated to make multivariate analysis." (PMID 35910854, 2022). "For these analyses, we excluded tumor-associated markers expressed in more than 90% (CK7, CK19, CKLMW, CKHMW, and MUC1) or less than 10% (vimentin and MUC2) of the tumor samples." (PMID 33494186, 2021). "The three “canonical” intestinal markers CDX2, CK20 and MUC2 were individually expressed by 56%, 54% and 54% of tumours, respectively, with 79% of all cases showing at least one of such markers." (PMID 33963925, 2021). "Tumor specimens with high MUC2 expression were adversely prognostic for all three endpoints, disease-specific survival (DSS), local recurrence-free survival (LRFS), and metastasis-free survival (MeFS) (all p < 0.0001), at the univariate level." (PMID 34300195, 2021). "The expression of MUC5A and MUC2 genes was higher in stage IV of the tumor than in other stages (P<0.05)." (PMID 35572847, 2021). "In conclusion, we observe that patients with stage II CRC with low expression of MUC2 in the tumor respond better when treated with adjuvant chemotherapy." (PMID 33823840, 2021). "In vitro, RDEA119 was found to efficiently inhibit MUC2 transcription in mucin-producing LS174T CRC cells as well as in PMP tumor explants by reducing ERK1/2 phosphorylation." (PMID 34885075, 2021). "Although the role of MUC2 in CRC is supposed to be tumor suppressive, the expression of the MUC2 gene or other MUC genes in CRC is controversial in different studies." (PMID 32695780, 2020). "Based on the current and updated evidence, an understanding of the potential tumor-suppressive role of MUC2 in CRCs is forthcoming, and more investigations are needed to uncover its underlying mechanism." (PMID 32695780, 2020). "Using the presence of expression in more than 10% tumour cells as cut-off for all 3 stains (MUC2, MUC5AC, AB/PAS), 670 (53%) cancers were classified as ‘triple negative’." (PMID 32488651, 2020). "It has been reported that overexpression of Muc2 in CRC helps tumor cells to evade recognition by anti-tumor immune effector molecules, which contributes to the development of CRC." (PMID 32403433, 2020). "MCC are a unique histologic subtype in which greater than 50% of the tumor mass is composed of extracellular MUC2 protein." (PMID 32811515, 2020). "Since MUC2 is a tumour suppressor, whereas overexpression of MUC20 favours tumour progression, these data indicate that BAs facilitate tumour development under normal conditions, by altering the expression of these mucins." (PMID 33328627, 2020). "It was also reported that the MUC2 promoter was significantly more often hypermethylated in HCCs, than in non-tumour samples (~62% vs. ~19%, respectively)." (PMID 30875782, 2019). "The association between the MUC2 expression level in CRC tissues and tumor site was investigated in 5 studies." (PMID 29967641, 2018). "PAS staining and immunohistochemical staining of human CRC tissue also showed the absence of goblet cells and MUC2, while both the amount of goblet cells and the secretion of MUC2 were normal in the tumor-adjacent tissue." (PMID 30498394, 2018).
tumor (continued). "The association between the MUC2 expression level in CRC tissues and tumor size was investigated in 2 studies." (PMID 29967641, 2018). "MUC2 has been shown to serve as a tumor suppressor in mice and creates a mucin protein that is a protective barrier in the intestinal epithelium." (PMID 29899320, 2018). "At the same time celecoxib significantly induced apoptosis in treated tumor tissue, confirming our in vitro findings of dual inhibitory effects of celecoxib on MUC2 production and cell viability." (PMID 29290997, 2017). "Mucinous appendix cancers are a unique histologic subtype in which greater than 50% of the tumor mass is composed of extracellular mucin 2 (MUC2) protein." (PMID 29290997, 2017). "Contrary to these cancer-promoting mucins, MUC2 interacts with inflammatory pathways and helps protect against tumor development." (PMID 28978023, 2017). "The importance of this subtle inflammatory response in Muc2−/− mice was also evident from exacerbation of the tumor phenotype in double mutant Muc2−/−; Apc1638N/+ or Muc2−/−; ApcMin/+ mice." (PMID 29069719, 2017). "Analysis of the excised tumor tissue following sacrifice demonstrated significant reduction of MUC2 mRNA and protein expression, suggesting that celecoxib effectively inhibited mucin production in vivo." (PMID 29290997, 2017). "We observed suppressed E-cadherin expression and decreased CREB/ATF-1 phosphorylation in MUC2-silenced tumor cells after rIL-6 treatment." (PMID 28725043, 2017). "In normal goblet cells, AGR2 is required for folding and processing of secreted (MUC5AC) and membranous mucins (MUC1, MUC2, MUC5B;) which have also been implicated in various tumor-promoting processes." (PMID 29267283, 2017). "MUC2, MUC5AC, and MUC6 were significantly associated with MMR status and tumor border configuration." (PMID 27298226, 2016). "The results showed that MUC2 expression was markedly higher in infected gastric tissues, especially in infected tumor tissues." (PMID 27835575, 2016). "KLF4 expression is negatively correlated with MUC2 in these signet ring carcinomas (‘T': tumor tissue)." (PMID 27277677, 2016). "It has been demonstrated that the mucus in tumor tissue is characterized by MUC2 and obviously increased in CRMAC." (PMID 26356816, 2015). "MUC2 deficient mice develop adenocarcinomas and when crossed with APC deficient mice, the result is accelerated tumor development and metastasis." (PMID 26230607, 2015). "IL-6 neutralization attenuated tumor formation by MUC2 RNAi cells; it also increased CD8 T cell infiltration into the peritoneum." (PMID 25322805, 2014). "We did not observe any changes in levels of amylase or cytokeratin 19, or the mucins MUC1, MUC2 or MUC5AC in rapamycin-treated KC PTEN tumours." (PMID 24717934, 2014). "MUC2 expression is also related to a better prognosis of neoplasms in the stomach, pancreas and bile duct." (PMID 25551773, 2014). "To investigate the role of MUC2 in a native tumor environment, we examined the effects of MUC2 knockdown in an orthotopic immune-competent animal model." (PMID 25322805, 2014). "In the present study, the secretion of IL-6, RANTES and GCSF was increased in the MUC2-knockdown tumor cells in comparison to the SR tumor cells." (PMID 25322805, 2014). "Taken together, to the best of our knowledge, this is the first study indicating that the immune response to cancer cells plays an important role in tumor growth regulated by MUC2." (PMID 25322805, 2014). "This pattern differs from the expression patterns involving MUC1, MUC2 or MUC4 that are related to a poor prognosis in neoplasms of other organs." (PMID 24722639, 2014). "The difference of MUC2 methylation between the tumor and non-tumor groups was statistically significant (p < 0.0001)." (PMID 23347460, 2013). "MUC2 promoter was hypermethylated in 62.2% (46/74) of HCCs, and in only 18.9% (14/74) of non-tumor samples." (PMID 23347460, 2013).
tumor (continued). "The relationship between MUC2 mRNA status and known clinicopathologic factors in 74 tumor tissues were examined." (PMID 23347460, 2013). "MUC2 promoter was hypermethylated in 62.2% (46/74) of HCCs, and in 18.9% (14/74) of non-tumor samples; partial methylated in 28.4% (21/74) vs. 62.2% (46/74); unmethylated in 9.4% (7/74) vs. 18.9% (14/74)." (PMID 23347460, 2013). "For pap-type GC, expressions of CTSE, MUC5AC, and MUC2 were considerably strong in both the tumor lesion and surrounding mucosa, which are quite different from the expression patterns of tub1/tub2-type GC." (PMID 23451082, 2013). "Meanwhile, the MUC2 mRNA was decreased in tumor tissues with age > = 40 years than those with age < 40 years in HCC patients (Mean -ΔCt ± SE, -5.57 ± 1.89 and −1.29 ± 0.80, respectively) (p < 0.001)." (PMID 23347460, 2013). "MUC1 and MUC4 stained the apical portion of glandular tumor cells and the membrane of intermediate and epidermoid tumor cells while MUC2 and MUC5AC stained the cytoplasm of glandular, mucous, and intermediate tumor cells." (PMID 24367734, 2013). "But the MUC2 mRNA was elevated in tumor tissues with AFP > = 30 (μg/l) than those with AFP < 30 (μg/l) in HCC patients (Mean -ΔCt ± SE, -3.73 ± 0.75 and −6.25 ± 0.94, respectively) (p = 0.040)." (PMID 23347460, 2013). "We examined histological phenotype of tumors of AFPC or NEC containing the composite tumor by evaluating immunohistochemical expressions of MUC2, MUC5AC, MUC6, CDX2, and SOX2." (PMID 22482081, 2012). "These were Defcr4, S100A9, Igfbp5, Slc30a2 and Lgr5 (leucine-rich repeat containing G protein coupled receptor 5) which were up-regulated and Mptx, Slc26a3, Retnla, Muc2 and Hpgd (hydroxyprostaglandin dehydrogenase 15) which were down-regulated in tumours." (PMID 20459814, 2010). "In this study, the incidence of HGM expression was significantly higher in C-Ca than in D-Ca among early-stage tumours, whereas the incidence of MUC2 expression was significantly lower in cases of C-Ca than in those of D-Ca among the advanced-stage tumours." (PMID 17262083, 2007). "It is believed that PMP is characterized by the production of MUC2, a gel forming mucin that forms strong bonds with the surrounding stroma and is also believed to have tumor suppressor activities." (PMID 16945158, 2006). "This is a neoplastic disease of MUC2-expressing goblet cells, which collectively overexpress MUC2 because of their increase in number." (PMID 15967038, 2005). "The mucosecreting tumoural subtypes presented a completely different pattern of mucin expression, including a high and predominant MUC2 expression." (PMID 14760390, 2004). "Anti-MUC2 antibodies stained rare tumour cells in PAC120 p4 and in HID16, HID28 and HID33, while signet-ring cells were uniformly stained in HID25 and in the other HID variants." (PMID 14760390, 2004). "These antibodies should prove useful in the study of MUC2 structure and function, and in the diagnosis of some tumours." (PMID 8512804, 1993). "However, Faecalibaculum was significantly negatively correlated with tumor volume and positively correlated with MUC2 and butyric acid." (PMID 39924893, 2025). "Examining PMP tumour cells or cellular mucin in vitro alongside specific microorganism in a stromal environment, such as with MUC2-secreting human intestinal cell lines, could provide a new useful research model." (PMID 40599846, 2025). "MUC2 expression was significantly higher in cores histologically classified as mucinous, compared to non-mucinous, and MUC2 expression was significantly higher in high grade tumours." (PMID 41105300, 2025). "Thus, MUC2 plays a critical role in altering the immune landscape within the tumor microenvironment, favoring cancer growth." (PMID 40330466, 2025).
tumor (continued). "After cellular annotation of the 6 tumour cell types based on marker gene expression, we were able to identify the following: C0 PSCA+ tumour cells, C1 CLDN7+ tumour cells, C2 UBE2C+ tumour cells, C3 MUC6+ tumour cells, C4 CHGA+ tumour cells and C5 MUC2+ tumour cells." (PMID 38894657, 2024). "In summary, MUC2’s critical role in the gastrointestinal tract, its association with CRC progression, and its regulation by various factors underscore the importance of investigating its impact on the immune landscape within the tumor microenvironment." (PMID 39926604, 2024). "Alcian blue and immunohistochemical staining for MUC2, ZO-1, and occludin expression in tumour tissues revealed increased mucin layer-related and tight junction protein expression in the intestinal wall, which strengthen the intestinal barrier, in the combined group." (PMID 38245554, 2024). "Aberrant MUC2 expression, such as reduced or absent expression, is associated with tumor progression, invasion, and metastasis." (PMID 39682117, 2024). "Endoplasm reticulum‐associated pathways, encompassing ‘Response to endoplasmic reticulum stress’, ‘Endoplasmic reticulum unfolded protein response’ and ‘Intrinsic apoptotic signalling pathway in response to endoplasmic reticulum stress’, exhibited a predominant focus within C5 MUC2+ tumour cells." (PMID 38894657, 2024). "Moreover, the MGL mutant was unable to recognize Tn epitopes on tumor cell lines or its previously established Tn-containing ligands such as MUC1 or mucin 2 (MUC2)." (PMID 38069400, 2023). "Regarding MUC2, a surrogate marker for the intestinal phenotype, it can be hypothesized that, if the premalignant lesion is IM, the tumor cells will inherit a MUC2-positive immunophenotype." (PMID 37240039, 2023). "Furthermore, we identified eight hub genes (VSNL1, TH, PCP4, IGDCC3, RAD51AP2, MUC2, BUB1, and BUB1B) that promoted tumor progression and were associated with prognosis according to the Kaplan–Meier and ROC curve analyses." (PMID 36979826, 2023). "Unlike MUC2, cell surface-linked Mucin 1 (encoded by Muc1) is often associated with tumor-induced changes in host immunity." (PMID 37966243, 2023). "In addition, the MUC2-positive (goblet marker) cells were also depleted in tumor tissues compared to adjacent normal tissue, which was also verified by IHC staining." (PMID 35974387, 2022). "It is normally expressed in the healthy epithelium of the colon but the alteration of MUC2 expression of tumor cells may play an important role in tumor progression." (PMID 34885019, 2021). "We found MUC2 over-expression in GATA3-mutant tumor than normal samples." (PMID 33462316, 2021). "The inflammation and tumor suppression role of MUC2 may appear paradoxical when it is observed that MUC2 expression is increased in mucinous CRC." (PMID 33808549, 2021). "The location of MUC2 positive tumour cells appeared to be more variable and could be superficially, central/marginal, or in a mosaic pattern." (PMID 32488651, 2020). "Therefore, this study was conducted to investigate the serum levels of MUC2 in BC patients and the relationship with tumour progression and known prognostic parameters." (PMID 30682816, 2019). "Fourteen of the mutated genes in this tumor are involved in metabolism (endogenous molecules as well as drugs), small molecule biochemistry, and cancer: AATF, ATF71P, CRIPAK, CROCC, CYP2A6, DOCK5, GPAT2, KRTAP4–9, LSM14A, MUC2, MYO1F, RHOQ, SUFU, and UTRN." (PMID 29259192, 2017). "MUC2 positive tumours showed reduced Snail expression, suggesting bile acids could regulate tumour behaviour in oesophageal and colon cancers." (PMID 29383197, 2017). "MUC2 is a gel-forming glycoprotein that is thought to be secreted by neoplastic goblet-like epithelial cells and produces a mucinous protective environment surrounding the tumor cells." (PMID 29290997, 2017).
tumor (continued). "Apart from revealing the inhibitory effects of BR/NAC on tumor growth, this animal study also indicated, consistent with our in vitro observations, that BR/NAC therapy remarkably diminished the tumor production of the membrane-associated mucin MUC1, as well as of the secreted mucins MUC2 and MUC5AC." (PMID 26436698, 2015). "Mutations identified from our study in genes such as MUC16, MUC2 and ODZ1 could shed new insights into metastasis-promoting pathways in tumor cells." (PMID 26555578, 2015). "Similarly, other tumor-derived factors, such as gangliosides, mucin 2 (MUC2), and high-mobility group protein B1 (HMGB1), have been shown to trigger apoptosis of TADCs." (PMID 26690204, 2015). "These experiments suggest that MUC2 knockdown enhanced IL-6 secretion and promoted tumor growth." (PMID 25322805, 2014). "In the absence of NK cells, macrophages, B and T cells, the mean tumor mass of mice implanted with the SR cells was similar to the mean tumor mass of mice implanted with MUC2 RNAi-1 cells, suggesting that the effects of MUC2 were dependent upon the presence of a competent immune system." (PMID 25322805, 2014). "Given the importance of a functional immune system for the effects of MUC2 on tumor growth, we further investigated whether cancer cell-secreted cytokines were involved in the tumor microenvironment." (PMID 25322805, 2014). "Interestingly, there was a good correlation between the mRNA expression level of MUC2 in control cultures and the existence of the mucinous component of the parent tumor." (PMID 23409082, 2013). "High levels of MUC2 expression in indolent human pancreatobiliary neoplasms with a favorable prognosis may be related to the tumor suppressor activity of MUC2." (PMID 23101681, 2012). "The model that included the three biomarkers (MUC1, MSLN, and MUC2) was superior to the model including four conventional pathologic features (lymph node status, histologic grade, tumor size, and resection margin status), although the difference just missed statistical significance (p = 0.07)." (PMID 22792233, 2012). "Abnormal glycosylation of MUC2 in LSLiM6 cells exposes Tn and sialyl Lex antigens on the surface of tumor cells, and these glycan epitopes are important in adhesive interactions with the basement membrane and vascular endothelium by binding E-selectin, which favors metastasis." (PMID 23056409, 2012). "Other mucins are aberrantly expressed in cancer and MUC2 was ascribed a tumor suppression function." (PMID 17553165, 2007). "Possibly MUC2 expression can be induced by external agents in CRC tumour cells." (PMID 16755296, 2006). "Recent studies reveal that PMP is a neoplastic disease of MUC2-expressing goblet cells." (PMID 16945158, 2006). "Haematogenous recurrence was significantly associated with MUC2-negative tumours (P=0.028) and CD10-positive tumours (P=0.039), compared with the control group." (PMID 15354218, 2004). "Peritoneal recurrence was significantly associated with HGM-positive tumours (P=0.022) and MUC2-negative tumours (P=0.0002), compared with the control group." (PMID 15354218, 2004). "In the present study, peritoneal recurrence was also strongly associated with MUC2-negative tumours." (PMID 15354218, 2004). "This analysis uncovered 2 tumor-associated epithelial populations, including a tumor-specific stem-like (tSTM, cluster 0) state defined by OLFM4 and LGR5, and a tumor-specific deep crypt secretory (tDCS, cluster 10) state characterized by REG4 with limited MUC2." (PMID 41282138, 2025). "In addition, positive expression of CDX2 and MUC2 in tumor cells was observed only in some areas, indicating that PGA mainly expressed gastric markers, intestinal epithelial differentiation was rare, and only a small amount of gastric-to-intestinal differentiation transition was observed." (PMID 40660594, 2025). "Thus, CCFM683 could prevent CRC by up-regulating MUC2, Claudin-1, and ZO-1, and promoting tumor cell apoptosis via the CLA-PPAR-γ axis." (PMID 39924893, 2025).